TERT (telomerase reverse transcriptase)
Diseases named in the same sentence as TERT in open-access papers (continued):
Sharing a sentence is not in itself a finding about the gene and the disease.
ischemic stroke (5 papers, 2015 to 2024). A stroke disorder caused by obstruction of blood flow to the brain, due to thrombotic (local blood clot formation) or embolic (due to a blood clot or other material traveling from another site) event. "Of these, TERT is an essential regulator of telomerase activity, and observational analyses suggest that TERT gene variants are related to ischemic stroke (IS) risk." (PMID 39180127, 2024). "Taken together, our results suggest a potential association between LTL related TERC, TERT gene variants and ischemic stroke risk." (PMID 28057933, 2017). "Our results revealed that polymorphisms in TERC and TERT genes have an association with susceptibility risk of ischemic stroke in a Chinese Han population." (PMID 28057933, 2017). "Cumulatively, our findings provide evidence that polymorphisms in TERC and TERT genes variation are associated with increased ischemic stroke risk." (PMID 28057933, 2017). "In this case-control study, we found that rs2853677, an intrinsic SNP within the TERT gene, was significantly associated with ischemic stroke risk according to both allele and genotype association analysis in a Chinese population." (PMID 28057933, 2017). "Subsequent model association analysis of another locus within TERT gene, rs2242652, also found that genotype “G/A” in the over-dominant model and genotypes “G/A” and “A/A” in the dominant model increased the ischemic stroke risk." (PMID 28057933, 2017). "The association between six TERT polymorphisms that tag the variation in this gene and development of MI and ischemic stroke over a 20-year follow-up period was examined in white and African-American ARIC study participants with no prior history of disease." (PMID 26201603, 2015). "TERC and TERT variants were found linked to ischemic stroke risk." (PMID 28057933, 2017). "The data showed that in rs2242652 of TERT gene, an enhanced risk of ischemic stroke was associated with the genotype “G/A” in the over-dominant model (OR = 1.45, 95% CI, 1.02–1.77; P = 0.038) and genotypes “G/A” and “A/A” in the dominant model (OR = 1.42, 95% CI, 1.01–2.01; P = 0.044)." (PMID 28057933, 2017). "All these results together with previous studies strongly implicate the involvement of TERT in ischemic stroke." (PMID 28057933, 2017). "TERT has been reported to be involved in the modulation of BBB integrity during ischemic stroke." (PMID 36299510, 2022). "To elucidate the association between LTL variation and ischemic stroke (IS) risk, we selected ten single nucleotide polymorphisms (SNPs) in three genes (TERC, TERT and RTEL1) that previously reported link to LTL, and genotyped SNPs of these genes in a case-control study." (PMID 28057933, 2017). "We hypothesize that these loci variant of the TERC and TERT genes could have shortened LTL, leading to increased possibility of having ischemic stroke." (PMID 28057933, 2017). "For further verification, potential core targets (STAT3, MMP2, ESR1, TERT, and MMP9 proteins) for ischemic stroke and core active ingredients (Tanshinol A, Tanshinol B, Tanshinone II A, and Przewaquinone C) for Salvia miltiorrhiza Bge. were further verified by molecular docking." (PMID 36133785, 2022). "Using PyMOL software, Discovery studio 4.5 client, and Autodock tools 1.5.6 software, the interaction between potential active compounds (Tanshinol A, Tanshinol B, Tanshinone II A and Przewaquinone C) and ischemic stroke related proteins (MMP2, STAT3, TERT, and ESR1) was studied." (PMID 36133785, 2022). "We then did Haplotype analysis to explore the connection between the TERT, RTEL1 haplotype and the risk of ischemic stroke, but no significant conclusion was found." (PMID 28057933, 2017).
laryngeal carcinoma (5 papers, 2013 to 2023). Carcinoma that arises from the laryngeal epithelium. "TERT promoter mutations were significant predictors of poor prognosis in patients with laryngeal cancer, as an independent variable, with respect to age, tumor localization, TNM stage, tumor invasion, lymph node metastasis, and smoking history." (PMID 36979671, 2023). "Carriers of the TERT Rs2736100 mutant heterozygote genotype (AC) have a significantly higher risk of laryngeal cancer compared to those with the normal wild-type genotype." (PMID 36013573, 2022). "We also determined the correlation between the protein expression levels of TERT and AP-1 in a laryngeal carcinoma tissue microarray using quantum-dot based immunofluorescence." (PMID 23946780, 2013). "The correlation coefficient between TERT and c-Fos mRNA expression in laryngeal carcinoma tissue samples was 0.574 (P<0.01), and the correlation coefficient between TERT and c-Jun mRNA expression was 0.809 (P<0.01)." (PMID 23946780, 2013). "TERT and telomerase are overexpressed in 85–90% of human cancers, and are closely correlated with the development of laryngeal carcinoma and the proliferation of laryngeal carcinoma cells." (PMID 23946780, 2013). "In conclusion, the results of this study indicate that TERT is capable of promoting cell proliferation via activation of the AP-1 subunits, c-Jun and c-Fos, in laryngeal carcinoma cells." (PMID 23946780, 2013). "TERT mRNA expression levels were positively correlated with c-Fos and c-Jun mRNA in human laryngeal carcinoma tissue." (PMID 23946780, 2013). "To examine the correlation between TERT and the AP-1 subunits c-Fos and c-Jun, we analyzed the correlation between TERT, c-Fos and c-Jun mRNA expression in 24 laryngeal carcinoma tissue samples using RT-PCR." (PMID 23946780, 2013). "TERT, c-Fos and c-Jun mRNA and protein were all observed to be expressed at high levels in HEp-2 cells and laryngeal carcinoma tissue samples." (PMID 23946780, 2013). "TERT mRNA expression was quantified using RT-PCR in 24 human laryngeal carcinoma samples, and TERT protein co-expression with AP-1 was investigated in a human laryngeal carcinoma tissue microarray using quantum-dot based immunofluorescence." (PMID 23946780, 2013). "In conclusion, this study indicates that TERT is important in cell proliferation in laryngeal carcinoma." (PMID 23946780, 2013). "In this study, we overexpressed and silenced the expression of TERT in the human laryngeal carcinoma cell line, HEp-2, using adenovirus-based vectors." (PMID 23946780, 2013). "TERT and AP-1 protein were expressed at high levels and positively correlated in laryngeal carcinoma tissues." (PMID 23946780, 2013). "In this study, we investigated the correlation between TERT and the major AP-1 proteins (c-Jun and c-Fos) during TERT-promoted laryngeal carcinoma cell proliferation." (PMID 23946780, 2013). "Additionally, the expression of c-Fos and c-Jun mRNA were both positively correlated with TERT expression in human laryngeal carcinoma tissues." (PMID 23946780, 2013). "We transfected HEp-2 laryngeal carcinoma cells with a TERT overexpressing adenovirus (Ad-TERT) and TERT shRNA silencing adenovirus (Ad-sh-TERT), and examined the effect on TERT and the AP-1 transcription factor subunits c-Fos and c-Jun using RT-PCR and western blot analysis." (PMID 23946780, 2013). "To test the hypothesis that TERT and AP-1 are overexpressed in laryngeal carcinoma cells and therefore could contribute to laryngeal carcinoma cell proliferation, we analyzed the mRNA and protein expression levels of TERT, c-Fos and c-Jun in HEp-2 cells and human laryngeal carcinoma tissue samples." (PMID 23946780, 2013). "It has been reported that p38/ERK activation induces AP-1 expression; therefore, we examined the relationship between TERT, p38, ERK, JNK and AP-1 in HEp-2 laryngeal carcinoma cells." (PMID 23946780, 2013).
laryngeal carcinoma (continued). "Using siRNA targeting, TERT is capable of inhibiting laryngeal carcinoma cell proliferation, but the mechanisms are not well understood." (PMID 23946780, 2013).
lung squamous cell carcinoma (5 papers, 2014 to 2025). "Elevated IL-10, IL-13, and TERT levels and reduced MCP-1/MCAF levels are associated with lung squamous cell carcinoma." (PMID 40292253, 2025).
medullary thyroid cancer (5 papers, 2016 to 2020). "A 2016 study of medullary thyroid cancer (MTC) and normal thyroid tissue samples quantified the TERT upstream promoter methylation at eight CpG sites." (PMID 32849278, 2020).
renal carcinoma (5 papers, 2014 to 2022). A carcinoma arising from the epithelium of the renal parenchyma or the renal pelvis. "In contrast, PUF60 overexpression in renal cancer cells stimulates telomerase reverse transcriptase (TERT) transcription due to PIF60’s binding to the TERT promoter." (PMID 36497066, 2022). "Similarly, the WT1 repressor downregulated TERT transcription in a renal carcinoma cell line where overexpression of WT1 suppressed both TERT and MYC mRNA levels via binding to their promoters." (PMID 33802026, 2021). "The role of PUF60/TERT in renal cancer was evaluated on cell growth in vitro and in vivo." (PMID 33061812, 2020). "Furthermore, WT1 dependent TERT repression in renal cancer cells involves upregulated expression of TERT repressors SMAD3 and JUN, as well as down-regulation of activators AP-2 and NFX1." (PMID 24550717, 2014). "While our current experimental data cannot tell whether PUF60 directly binds to TERT promoter or not, we will further determine the more detailed roles of the two proteins in regulating TERT expression and renal cancer cell growth in the future." (PMID 33061812, 2020).
systemic lupus erythematosus (5 papers, 2013 to 2026). An autoimmune multi-organ disease typically associated with vasculopathy and autoantibody production. "A recent genome-wide association study (GWAS) of Asian ancestry reported that single nucleotide polymorphism (SNP) in TERT (telomerase reverse transcriptase) was associated with systemic lupus erythematosus (SLE)." (PMID 34337078, 2021). "Interestingly, association of TERT rs7726159A has been shown to be associated with systemic lupus erythematosus (SLE) in East Asian populations." (PMID 33076992, 2020).
systemic sclerosis (5 papers, 2013 to 2023). A chronic disorder, possibly autoimmune, marked by excessive production of collagen which results in hardening and thickening of body tissues. "TERT-deficient BMMSCs (TERT-/-BMMSCs) lose their capacity to inhibit T cells and ameliorate the disease phenotype in mice with systemic sclerosis, whereas TERT transfection in these cells rescues their immunomodulatory functions." (PMID 31284662, 2019). "We report here the first case of isolated PPFE in a caucasian patient with systemic sclerosis (SSc) who does not carry TERT and TERC mutations." (PMID 29776440, 2018). "Therefore, in order to assess the therapeutic effect of TERT−/− BMMSCs, we infused either regular BMMSCs (WT; from TERT+/+ littermates) or TERT−/− BMMSCs into B6.Cg-Fbn1Tsk/J (Tsk/+) systemic sclerosis (SS) mice at 8 weeks of age and analyzed treatment response at 12 weeks of age." (PMID 24401839, 2014).
telomere syndrome (5 papers, 2017 to 2025). Accelerated aging syndromes often caused by inheritable gene mutations resulting in decreased telomere lengths. "In up to half of the cases of short telomere syndromes, the culprit is the autosomal dominant-inherited heterozygous mutations in the TERT gene, which exhibits the phenomenon of anticipation, driven by the short telomere length." (PMID 40231186, 2025). "TERC and TERT were initially the only genes tested in familial pulmonary fibrosis or telomere syndrome; other TRGs such as RTEL1 or PARN were later included in the NGS panel." (PMID 31796085, 2019).
triple-negative breast carcinoma (5 papers, 2016 to 2023). An invasive breast carcinoma which is negative for expression of estrogen receptor (ER), progesterone receptor (PR), and human epidermal growth factor receptor 2 (HER2). "Collectively, these data indicate that the rs10069690 SNV and TERT expression play a central role in triple-negative breast cancer (TNBC)." (PMID 36768147, 2023). "We found that the age at onset of patients with triple-negative breast cancer (TNBC) with the TERT rs10069690 TT genotype was significantly younger than of those with the CC genotype." (PMID 36768147, 2023). "Interestingly, the triple-negative breast cancer cell lines are the most resistant to ATRA-induced TERT repression." (PMID 35327497, 2022).
upper tract urothelial carcinomas (5 papers, 2014 to 2021). "However, it is currently unclear whether these mutations are all present in upper tract urothelial carcinomas (UTUC) including renal pelvic carcinoma (RPC) and ureter carcinoma (UC), although TERT promoter mutations were previously observed in these malignancies." (PMID 34093793, 2021).
adrenocortical carcinoma (4 papers, 2014 to 2025). "Molecular characterization of adrenocortical carcinomas (ACC) by The Cancer Genome Atlas (TCGA) has highlighted a high prevalence of TERT alterations, which are associated with disease progression." (PMID 34549366, 2022). "Whole genome doubling associated with decreased telomere length and increased TERT expression has been associated with disease progression in adrenocortical carcinomas in The Cancer Genome Atlas (TCGA) datasets." (PMID 34549366, 2022). "Additional studies are needed to address whether TERT alterations are enriched in rarer histologic variants of adrenocortical carcinomas such as the myxoid variant." (PMID 34549366, 2022). "Due to the rarity of these events in adrenocortical carcinomas there is insufficient data at present to comment on whether TERT structural variants in this tumor type exhibit a conserved breakpoint." (PMID 34549366, 2022). "In addition, the association between TERT promoter hypermehtylation and poor outcomes or progression was reported in brain tumors and adrenocortical carcinoma." (PMID 31285550, 2019). "While genomic amplification events for TERT at the 5p15.33 locus have been documented in multiple studies of adrenocortical carcinomas, other mechanisms of upregulation of TERT have been documented across various tumor types." (PMID 34549366, 2022). "A prior study of pediatric adrenocortical carcinomas had documented a high incidence of TERT amplifications in a relatively small cohort of patients (13 of 19, 68.4%) without evaluating for “hotspot” promoter mutation status." (PMID 34549366, 2022). "For 6 cases of adrenocortical carcinomas with TERT gene amplifications profiled using both NGS and FISH, the results of both testing modalities were concordant." (PMID 34549366, 2022). "Due to an association between whole genome doubling and TERT expression in a prior TCGA study, it has been suggested that TERT is required in a subset of adrenocortical carcinomas for telomere maintenance." (PMID 34549366, 2022). "As there is a paucity of prognostic biomarkers in adrenocortical carcinomas, we interrogated a large cohort of 169 cases (institutional cohort: 78, TCGA: 91) for TERT alterations and correlated the presence of these alterations with various clinicopathologic parameters and outcomes." (PMID 34549366, 2022). "To conclude, TERT promoter mutations are predominantly found in the subgroups of malignant endocrine tumors, such as malignant PGL and adrenocortical cancer, and the observation of C228T mutations in 12% of ACCs adds a new cornerstone to the mutational panorama of these tumors." (PMID 24803525, 2014). "In summary, the results of our study suggest that TERT alterations occur frequently in adrenocortical carcinomas and not in adrenal adenomas, and that copy number gains/amplifications are much more frequent compared to “hotspot” promoter mutations." (PMID 34549366, 2022). "In the current study, only a minority of adrenocortical carcinomas occurred in patients less than 20 years of age (institutional cohort: 4 of 78 cases; The Cancer Genome Atlas: 3 of 91 cases) and no TERT alterations were documented in these cases." (PMID 34549366, 2022). "Interestingly, adrenocortical carcinomas in both the institutional and TCGA cohorts showed a female predilection, irrespective of TERT status and the significance of this observation is unclear." (PMID 34549366, 2022).
B-cell lymphomas (4 papers, 2016 to 2018). "We have previously reported the presence of numerous clonally expanded integrations of the avian leukosis virus (ALV) in the TERT promoter region in chicken B-cell lymphomas, associated with slightly elevated TERT expression." (PMID 29657298, 2017). "Our lab has previously shown that the TERT promoter region is a common integration site in ALV-induced B-cell lymphoma." (PMID 29439385, 2018). "We observed increasing tumor clonality during progression of B-cell lymphomas and identified gene players (especially TERT and MYB) and biological processes involved in tumor progression." (PMID 29099869, 2017). "We have previously identified common proviral integrations in ALV-induced B-cell lymphomas, notably in the TERT promoter region, and in hemangiomas." (PMID 29099869, 2017).
basal cell carcinoma (4 papers, 2010 to 2018). A carcinoma involving the basal cells. "TERT promoter mutations were identified in 18 (56%) basal cell carcinomas and in 17 (50%) cutaneous squamous cell carcinomas." (PMID 24260374, 2013).
carcinoids (4 papers, 2017 to 2025). "Michele Simbolo and colleagues’ work on carcinoids reveals differential gene expression, with atypical carcinoids (AC) showing increases in genes such as TERT and SDHA, and typical carcinoids (TC) showing a loss in MEN1." (PMID 38539512, 2024). "Aggressive subsets of carcinoids have been suggested based on gene expression characteristics, genomic features, and high TERT expression." (PMID 39185963, 2025). "There were fewer CNAs in carcinoids than in carcinomas; however ACs showed a hybrid pattern, whereby gains of TERT, SDHA, RICTOR, PIK3CA, MYCL and SRC were found at rates similar to those in carcinomas, whereas the MEN1 loss rate mirrored that of TCs." (PMID 27873319, 2017).
carcinoma in situ (4 papers, 2018 to 2025). "Recurrent TERT-p mutations were identified in 18 out of 37 (48.6%) penile SCCs, including all 3 carcinoma in situ cases." (PMID 33635430, 2021). "Of 428 biopsy specimens, the TERT C228T mutation was detected in 9% (31/364) of normal urothelium, 27% (4/15) of urothelial dysplasia (UD), 50% (9/18) of UD suspicious for carcinoma in situ (CIS), and 58% (18/31) of CIS." (PMID 32533903, 2020).
cervical squamous cell carcinoma (4 papers, 2012 to 2025). A squamous cell carcinoma arising from the cervical epithelium. "Two independent studies performed in India and in Italy showed that 20% of cervical squamous cell carcinoma harboured TERT promoter mutations independently from the HPV status." (PMID 38033865, 2023). "We have previously shown that TERT mRNA expression was markedly higher in cervical squamous cell carcinoma derived SiHa cells carrying TERTp C250T compared to TERTp wild type cervical cell lines further indicating that such mutations play a major role in TERT activation." (PMID 41487579, 2025). "TERT, which encodes the catalytic subunit of the telomerase complex hTERT and have been found to be amplified or upregulated in more than 90% of squamous cell cervical carcinomas and 40% of CIN III lesions, had a fold change of 1.45, just below the selected cut-off." (PMID 22412903, 2012). "Of note, a recent study showed comparable levels of HPV16 E6 and a significant increase in TERT mRNA in cervical squamous cell carcinoma specimens mutated in the TERT promoter versus those not mutated, suggesting a synergistic effect of mutations and viral oncoproteins in telomerase expression." (PMID 36358677, 2022).